TLR4 (toll like receptor 4)
Diseases named in the same sentence as TLR4 in open-access papers (continued):
Sharing a sentence is not in itself a finding about the gene and the disease.
co-infection (18 papers, 2015 to 2025). "TLR4 is also necessary for the migrations induced by the co-culture, co-infection, and P. gingivalis alone (see proposed model)." (PMID 38612423, 2024). "In the presence of HIV-1 Tat and systemic S. pneumoniae co-infection, chronic morphine treatment resulted in a significant increase in both TLR4 and TLR2 expressions on inflammatory monocyte (Ly6C+) cell population." (PMID 26087960, 2015). "The TAK-242/siRNA-treated IAV+SA group exhibited markedly decreased mRNA levels of inflammatory factors (NF-κB, IL-6, TNF-α) and adhesion molecules (ICAM-1, VCAM-1) compared with the uninfected IAV+SA group, confirming TLR4 as the key receptor mediating co-infection-induced inflammation." (PMID 40572089, 2025). "For instance, in viral/bacterial coinfection, LPS has been seen to reduce the number of T cells recognizing the virus, particularly natural killers (NK), suggesting that TLR-4 may actually play an important role in viral-bacterial coinfections." (PMID 34200555, 2021). "Thus, the role of TLR4 and its downstream signaling in co-infection are worthy of further investigations." (PMID 25906258, 2015). "Therefore, our results demonstrate that TLR4 regulates the migration of OKs infected with the monoculture of P. gingivalis and the co-culture of P. gingivalis and F. nucleatum, as well as following co-infection by both bacteria." (PMID 38612423, 2024). "Here, we observed that PDCoV/PEDV co-infection only has a detectable effect on TLR4 modulation by 3 DPI and single-PDCoV induces TLR4 upregulation by 5 DPI, similar to TLR2." (PMID 36376395, 2022). "Most TLR mRNAs, including TLR4, TLR5, and TLR8 were upregulated in the severe group, consistent with viral and bacterial co‐infection that was common among severe cases." (PMID 33135345, 2020). "comprising differential modification of monocyte-driven inflammation in the event of co-infection as well as alterations in TLR2 and TLR4 mRNA expression." (PMID 29234642, 2017). "Chronic morphine and HIV-1 Tat, in the context of systemic S. pneumoniae co-infection, differentially modulated induction of TLR2/4, which consequently facilitated trafficking of TLR2 → CD3 + CCR5+ and TLR4 → Ly6C+(CCR5+/CXCR4+) immune cells into the CNS." (PMID 26087960, 2015). "Based on the microarray data, TLR4 and LBP were slightly but markedly upregulated (1.79- and 1.8-fold, respectively) in the H1N1-SS2 co-infection group." (PMID 25906258, 2015). "The TLR4 total protein levels remained unchanged after infecting OKs with the monocultures or co-culture or co-infection, indicating no impact on TLR4 protein levels." (PMID 38612423, 2024). "RSV has a number of surface proteins that can bind directly with TLR4 and/or TLR7, as well as intracellular receptors such as RIG-I, suggesting that VitD3 may be important in regulating viral or viral-bacterial co-infection." (PMID 32318074, 2020). "Matrine treatment significantly down-regulated the expression of TLR3, TLR4 and TNF-α although it, to some extent, suppressed p-IκBα expression, suggesting that TLR3,4/NF-κB/TNF-α pathway play an important role of Matrine in combating PRRSV/PCV2 co-infection." (PMID 27080155, 2016). "In this study, we confirmed that PRRSV/PCV2 co-infection increased both TLR3 and TLR4 expression." (PMID 27080155, 2016). "In co-infection studies with Campylobacter rectus, the presence of Pg modulates the placental response to C. rectus by reducing placental expression of toll-like receptor 4 expression, which did not reduce adverse pregnancy outcome." (PMID 26731111, 2016). "Individuals with HIV/HCV co-infection also had higher sCD163 and monocyte TLR-4 expression as compared to HCV- PLWH with and without AUD, as well as a trend towards increased I-FABP values at study enrollment reflecting damaged intestinal epithelium at that timepoint." (PMID 35371104, 2022).
co-infection (continued). "In addition, we also found that Asc−/− mice, caspase-1−/− mice, and Nlrp3−/− mice exhibited comparable mortality to WT controls following co-infection with P. chabaudi and C. rodentium, as did mice lacking the LPS sensors Tlr4 or caspase-11." (PMID 33440153, 2021). "TLR2, like TLR4, was enhanced in participants with TB or HIV, but not so among participants with TB/HIV coinfection, pointing to disease-specific factors modulating expression." (PMID 38660059, 2024).
colorectal tumors (18 papers, 2011 to 2025). "TLR4 expression in breast and colorectal tumors has also been associated with a poor clinical outcome." (PMID 28116318, 2016). "LPS accelerated the growth and liver metastasis of colorectal tumors via Toll-like receptor 4 (TLR4) and nuclear factor kappa-B (NF-κB) pathway." (PMID 36341334, 2022). "Being inflammatory response mediators, overexpression of TLR4 and NFκB is reported in response to Fusobacterium infection in colorectal tumors." (PMID 35252868, 2022). "Activation of IL-6/p-STAT3/c-MYC signaling was demonstrated to enhance colorectal tumor growth in a TLR4-dependent manner." (PMID 34898475, 2021). "Fusobacterium nucleatum is significantly elevated in human colorectal tumors compared to that in adjacent healthy tissue, Fusobacterium nucleatum stimulates NF-κB by activating TLR4 signaling and facilitates tumor development." (PMID 32050430, 2020). "Fusobacterium nucleatum promotes M2 macrophage polarization via a TLR4-dependent mechanism in the colorectal tumor." (PMID 32050430, 2020). "We found that a strong TLR4 immunoreactivity predicts a worse prognosis in patients with a local colorectal tumor." (PMID 32424768, 2020). "Recent work has suggested that F. nucleatum can favor TLR4-mediated M2 polarization within colorectal tumors, suggesting that the immune response to these bacteria is context-dependent and heterogeneous, with the local environment regulating functional outcomes." (PMID 31249571, 2019). "TLR4 activation in nontumor host cells increased the development of colitis-associated colorectal tumors and diethylnitrosamine-induced liver cancer in animal models." (PMID 28116318, 2016). "We, therefore, aimed to investigate the potential of the TLR4 antagonist, IAXO-102, to attenuate gastrointestinal inflammation as well as supress tumour activity in a colorectal-tumour-bearing mouse model of GIM induced by CPT-11." (PMID 35962138, 2022). "Having demonstrated the link between TLR4/NF-κB and TNF-α/NOS2 induction in colorectal tumors, we focused our attention to elucidate the immunomodulatory effect of all-trans retinoic acid in NOS2 and TNF-α expression in inflamed colonic mucosa cultures." (PMID 28408791, 2017). "However, the transcript levels of NFκB and TLR4 remain unaltered in Fusobacterium-high tongue tumors, unlike colorectal tumors wherein the activity as well as transcriptional elevation is observed upon Fusobacterium infection." (PMID 35252868, 2022).
leukemia (18 papers, 2010 to 2024). A malignant (clonal) hematologic disorder, involving hematopoietic stem cells and characterized by the presence of primitive or atypical myeloid or lymphoid cells in the bone marrow and the blood. "Our work provides proof-of-concept that genome destabilizing events causing secondary leukemia can be prevented by a peptide blocking TLR4 activation." (PMID 34222016, 2021). "Moreover, our data are in agreement with a recent paper that showed an interaction of NPM1 with myeloid differentiation protein-2 (MD-2), a protein that associates with TLR4, in human leukemia monocytic cell line THP-1." (PMID 34134693, 2021). "We analysed bulk RNAseq datasets to verify the role of BEVs on the TLR4 pathway in THP‐1 monocytic cell line derived from human leukaemia." (PMID 35064769, 2022). "Further studies are necessary to elucidate the role of the TLR1, TLR4, TLR5, TLR6, TLR9, and CD14 polymorphisms in the pathogenesis of leukemia." (PMID 36071076, 2022). "On the other hand, the arising ROS level can oxidize HMGB1, which makes it more liable to bind to TLR4, and then leads to the deterioration of leukemia cells." (PMID 34933679, 2021). "Our results showed strong TLR4 expression, similar to that observed in other leukemia cells, normal eosinophils, and neutrophils." (PMID 32903598, 2020). "Although TLR4 expression in EoL-1 cells is similar to that in other leukemia cells, EoL-1 cells undergo apoptosis subsequent to S100A8 and S100A9 treatment." (PMID 32903598, 2020). "There are few reports regarding the potential roles of TLR2 and TLR4 in the pathogenesis of leukemia." (PMID 30774831, 2018). "Our data on TLR4 3725G>C genotype frequencies are comparable to the reported frequencies in leukemia study on Caucasian population." (PMID 21864388, 2011). "Furthermore, the TLR4/Myeloid differentiation primary response 88 (MyD88) signaling in the leukemic cells seems important for leukemia cell growth, disease development and chemosensitivity in human AML." (PMID 35163998, 2022). "TLR4 agonists have been developed and are used as vaccine adjuvants; whether TLR4 agonists should be tried to enhance antileukemic graft versus leukemia reactivity in allotransplant recipients require further investigation in experimental studies." (PMID 35163998, 2022). "LPS was chosen to avoid TLR4 activation by endogenous ligands (such as proteins released after dysfunctionalisation of mitochondria), which themselves induce the expression and release of IL-6 and other important factors required for leukaemia cell survival." (PMID 27322212, 2016). "Our work has provided evidence for even another detrimental outcome of TLR4 signaling in cancer patients undergoing chemotherapy, i.e. leukemia-inducing chromosomal damage in healthy HSPCs without killing the cells." (PMID 34222016, 2021). "Recently, we showed that also in ECs and VSMCs cross-talk between IFNγ and TLR4 resulted in augmented STAT1 phosphorylation and increased expression of the chemokine CXCL10 and the adhesion molecule ICAM-1 as well as adhesion of U937 leukemia cells to ECs, in a STAT1- and TLR4-dependent manner." (PMID 25478796, 2014).
lymphoma (18 papers, 2010 to 2025). A malignant (clonal) proliferation of B- lymphocytes or T- lymphocytes which involves the lymph nodes, bone marrow and/or extranodal sites. "Specifically, it prevents lymphoma by modulating the TNF-induced TLR4/MyD88/NF-κB axis, thereby reducing lymphoma incidence in Eμ-Myc mice." (PMID 39619672, 2024). "Empirical evidence suggests that butyrate-producing Eubacterium inhibit lymphoma development by attenuating the TNF-activated TLR4/MyD88/NF-κB signaling cascade." (PMID 38774867, 2024). "Together, these data suggest that spinal cord TLR4 signaling is critically required for the lymphoma-induced itch in both sexes." (PMID 36520531, 2023). "Potential indications and combinations of systemic TLR4 agonist are likely to be very diverse as exemplified by our results in colorectal and lymphoma models, both as monotherapy and in combination with a therapeutic monoclonal antibody like rituximab." (PMID 37223101, 2023). "Rhamnogalacturonan II (RG-II), a component of pectin that can be produced through bacterial fermentation, showed a preventive effect against lymphoma by increasing the DC-based immune response through the toll-like receptor 4 (TLR4) signaling pathway." (PMID 36615814, 2022). "A synthetic toll-like receptor 4 (TLR4) agonist resulted in T-cell inflammation of the tumor microenvironment (TME) to cure lymphomas." (PMID 34872521, 2021). "We demonstrate here in a bilateral model of A20 lymphoma that IT treatment of only one tumor with the synthetic TLR4 agonist GLA at the highest dose evaluated (50 μg) cured ~ 50% of mice, indicating the induction of a systemic immune response." (PMID 32974162, 2020). "In fact, TLR4 is increasingly considered a promising therapeutic target for solid cancers, and TLR4 activation by low doses of endotoxic LPS from E.coli showed therapeutic promise in inhibiting the progression of osteosarcoma, lymphoma, subcutaneous glioma, and osteosarcoma." (PMID 36678520, 2022). "S100A9 also interacts with TLR4 and promotes tumor growth in prostate tumor and lymphoma models." (PMID 29795379, 2018). "It has been reported that S100A9 could recruit additional MDSC into the tumor microenvironment by binding to RAGE and S100A9 interaction with TLR4 is critical for tumor growth in lymphoma." (PMID 27020242, 2016). "Hence, the effect of S100A9 and TLR4 on the growth of TRAMP prostate tumors is also reflected in the growth of EL4 lymphoma." (PMID 22470535, 2012). "In a lymphoma mouse model, it is shown that intratumoral injection of TriMix mRNA, encoding costimulatory molecules CD70, CD40 ligand, and constitutively active toll-like receptor 4 (TLR4), induces systemic tumor-specific T cell responses independent of the co-delivery of tumor antigen." (PMID 34262573, 2021). "Lymphoma cells secrete TNF‐α, which enhances TLR4‐mediated signaling in intestinal B cells and in turn inhibits malignant growth of lymphoma." (PMID 40727252, 2025). "Therefore, we next investigated whether EL4 lymphoma growth was also influenced by TLR4 expression." (PMID 22470535, 2012). "We also show here that TLR4 expression, like S100A9 expression, influences the growth of the EL4 lymphomas." (PMID 22470535, 2012). "It has also been shown that treatment with Q compounds has a similar effect on EL4 lymphoma growth as seen in animals lacking either S100A9 or TLR4 expression." (PMID 23667563, 2013). "Intratumoral (IT) injections of Glucopyranosyl lipid A (G100), a synthetic toll-like receptor 4 (TLR4) agonist formulated in a stable emulsion, resulted in T-cell inflammation of the tumor microenvironment (TME) and complete cure of 60% of mice with large established A20 lymphomas." (PMID 32974162, 2020). "After inoculation with EL4 lymphoma cells the expression level of TGFβ was increased in C57BL/6 and RAGE−/−, but not in S100A9−/− or TLR4−/− animals." (PMID 22470535, 2012).
oral squamous cell carcinoma (18 papers, 2012 to 2026). "BACKGROUND: This study examined the Porphyromonas gingivalis-derived lipopolysaccharide (P. g-LPS)-activated-toll-like receptor 4 (TLR4) pathway and its association with resistance to chemotherapy in oral squamous cell carcinoma (OSCC) cells." (PMID 41894086, 2026). "Moreover, previous investigations revealed that TLR4 was functionally expressed in oral squamous cell carcinoma cells, and high level of TLR4 was linked to a short survival rate." (PMID 34158059, 2021). "This study aimed to analyze and correlate the expression of TLR4 and PD‐L1 with the immune response, clinical characteristics, and prognosis of oral squamous cell carcinomas (OSCC)." (PMID 40762187, 2025). "While prior studies have implicated extracellular ENO1 in CD14-dependent TLR4 signaling in monocytes and a paracrine ENO1/TLR4/IL-6 axis driving metastasis in oral squamous cell carcinoma, its direct interaction with TLR4 in GBM remained unexplored." (PMID 41353343, 2025). "This study aims to investigate the expression of TLR4 in the epithelium surrounding oral squamous cell carcinomas (OSCC) in relation to its inflammatory microenvironment." (PMID 35327577, 2022). "Previous studies have indicated that LPS-induced HIF-1α stabilization is mediated by the TLR4/NF-κB signaling pathway under normoxia in immune cells and oral squamous cell carcinoma." (PMID 35464826, 2022). "In addition, ICA has been demonstrated to attenuate the growth and invasion ability of Human oral squamous cell carcinoma in vitro and in vivo by inducing the down-regulation of Toll-Like Receptor 4 (TLR4)/ NF-κB pathway." (PMID 33849528, 2021). "Our results confirm that TLR3 and TLR4 are highly expressed in oral squamous cell carcinoma (OSCC)." (PMID 27191981, 2016). "Reportedly, the interaction between the TLR4/NF-κB signaling pathway and HIF-1α contributes to tissue damage and tumor progression in pancreatic ductal adenocarcinoma, oral squamous cell carcinoma, and lung ischemia-reperfusion injury." (PMID 35464826, 2022). "A feedback mechanism was found in oral squamous cell carcinoma (OSCC), where the activation of TL3 and TLR4 induced the expression of HIF-1α; in addition, HIF-1α bound to the promoter of TLR3 and TLR4, increasing their expression." (PMID 35565420, 2022). "Thus, western blot assay was used to verify our suspicion that RETNLB played the tumor-promoting effect in oral squamous cell carcinoma cells through regulating the TLR2 and TLR4." (PMID 34158059, 2021).